ZNF440 (zinc finger protein 440)
Description:
May be involved in transcriptional regulation.
Synonyms: FLJ37933
Tractability: PROTAC: ubiquitination databases record sites on it.
Gene: Protein-coding gene on chromosome 19 (11,814,273 to 11,835,216, forward strand). Ensembl gene ENSG00000171295.
Subcellular location: Nucleus
Subcellular location (Human Protein Atlas): Nucleoplasm
Pathways (Reactome):
Gene expression (Transcription): Generic Transcription Pathway
Gene Ontology:
Molecular function: protein binding; DNA-binding transcription factor activity, RNA polymerase II-specific; RNA polymerase II transcription regulatory region sequence-specific DNA binding
Biological process: regulation of transcription by RNA polymerase II; regulation of DNA-templated transcription
Cellular component: nucleus
Genetic constraint (gnomAD): Loss-of-function variants: 47 observed, 51.48 expected, observed/expected ratio (o/e) 0.91, 90% interval 0.72 to 1.16. The upper end of that interval is the gene's LOEUF score, 1.16, which puts it in group 5 of 6, group 1 being the genes least tolerant of losing a copy. Missense variants: 703 observed, 735.68 expected, observed/expected ratio (o/e) 0.96, 90% interval 0.9 to 1.02. Synonymous variants: 255 observed, 247.88 expected, observed/expected ratio (o/e) 1.03, 90% interval 0.93 to 1.14.
Homologues: Orthologues: chimpanzee ZNF440 (98% identical), macaque ZNF440 (72% identical), mouse Zfp78 (29% identical), Drosophila melanogaster CG3281 (20% identical), Drosophila melanogaster CG2712 (18% identical), Drosophila melanogaster Phs (17% identical). Paralogues in human: ZNF69 (76% identical), ZNF439 (67% identical), ZNF763 (51% identical), ZNF20 (49% identical), ZNF491 (45% identical), ZNF555 (39% identical), ZNF77 (36% identical), ZFP90 (34% identical), ZNF778 (34% identical), ZNF404 (33% identical), ZNF560 (33% identical), ZNF596 (33% identical), and 50 more.
Diseases named in the same sentence as ZNF440 in open-access papers:
ZNF440 is named in the same sentence as 4 diseases in open-access papers, as found by Europe PMC text mining. Sharing a sentence is not in itself a finding about the gene and the disease. The quoted sentences say what the papers report.
lung carcinoma (1 paper, 2022). "Most of these sites are located in genes that have been well-established to be implicated in lung cancer development except TMEM120B and ZNF440." (PMID 35768804, 2022).
lung squamous cell carcinoma (1 paper, 2023). "TMEM120B, HMOX2, CALCOCO2, LONP2, ZNF440, CLCC1, and CHMP3 were identified to be optimal prognostic factors for lung squamous cell carcinoma (LUSC)." (PMID 36999050, 2023).
melanoma (1 paper, 2023). A malignant, usually aggressive tumor composed of atypical, neoplastic melanocytes. "For instance, MEF2A, EMP2, ZNF440, PIGL, FRMD4B, and HIF3A are not only downregulated in TCGA-SKCM melanoma samples but also essential for restraining tumor growth in CRIPSR KO screens." (PMID 37904237, 2023).
tumor (2 papers, 2022 to 2023). "Interestingly, significantly negative correlations between chr12:122215052A > I level and TMEM120B expression, chr19:11945758A > I level and ZNF440 expression, chr1:109474650A > I level and CLCC1 expression, chr16:48388244A > I level and LONP2 expression, were observed in LUSC tumor tissues." (PMID 35768804, 2022).